IL18 (interleukin 18)
Diseases named in the same sentence as IL18 in open-access papers (continued):
Sharing a sentence is not in itself a finding about the gene and the disease.
glomerulonephritis (9 papers, 2014 to 2023). A renal disorder characterized by damage in the glomeruli. "Macrophages also produce IL-23 and IL-18, which contribute to the generation of Th17 and Th1 T cell subsets, respectively, in glomerulonephritis." (PMID 33676416, 2021). "In glomerulonephritis, increased production of the cytokines IL-23 and IL-18, generated by antigen presenting cells, induces the expansion of IL-17-producing cells and interferon-γ-producing cells, respectively." (PMID 33676416, 2021). "In human mesangial cells, inhibition of 5-lipoxygenase and cyclooxygenase, which play important roles in the pathogenesis of glomerulonephritis in childhood, resulted in IL-18-induced proinflammatory cytokine release and cellular proliferation of these cells." (PMID 29514661, 2018). "Blocking IL-23 or IL-18 cell signals may therefore offer an approach to reduce inflammation and increase PD-1 expression in glomerulonephritis, which could be tested in relevant animal models." (PMID 33676416, 2021). "A role of IL-18 has been reported in several experimental animal models of glomerulonephritis." (PMID 33732720, 2021). "Thus, in experiments with several animal models, the suppression of IL-18 signaling has been shown to be protective against glomerulonephritis." (PMID 33732720, 2021). "Further IL-18 deletion shows renal protective role in mice of ischemic and nephrotic AKI as well as LN and glomerular nephritis." (PMID 36379914, 2022). "In MRL/MpJ-Tnfrsf6lpr mice exhibiting lupus like autoimmune syndrome, vaccination with IL-18 cDNA in order to inhibit IL-18 showed that IFN-y production was suppressed and mice showed less glomerulonephritis and renal damage." (PMID 36032110, 2022). "Although the IL-18 level hinted at development of glomerulonephritis and genotype of IL-18 rs1946518CC was related with a higher level of IL-18 mRNA, the current study revealed that rs1946518 may not be associated with clinical symptoms and pathology grade in IgAN." (PMID 34354705, 2021).
lung adenocarcinoma (9 papers, 2018 to 2025). A carcinoma that arises from the lung and is characterized by the presence of malignant glandular epithelial cells. "The NLRP3 inflammasome enhances lung adenocarcinoma cell A549 proliferation by activating the IL-1β/ERK/CREB and IL-18/AKT/CREK signaling pathways." (PMID 40026444, 2025). "In the absence of Trem2, TAM in primary lung adenocarcinoma were unable to express IL18bp, which normally intercepts IL-18 and prevents IL-18-dependent activation of NK cells." (PMID 39430099, 2024). "Because of no clear conclusion confirming the specific role in lung adenocarcinoma, TLR4 attracts our attention, which enables to stimulate NLRP3 inflammasomes via enhancing the activation of nuclear factor-κB (NF-κB), releasing more pro-inflammatory cytokines like IL-1β and IL-18." (PMID 37553698, 2023).
Neonatal sepsis (9 papers, 2017 to 2025). Systemic inflammatory response to infection in newborn babies. "These disorders are characterized by a huge persistent elevation of IL‐18 in the blood as in neonatal sepsis and, in fact, we observed a 2‐fold overexpression of the IL18 gene in FIR‐affected infants." (PMID 33006196, 2021). "In a neonatal sepsis mice model, treatment with IL-17A-neutralizing antibody mitigated IL-18-related disease deterioration." (PMID 32849528, 2020). "First, IL-18 was found to be higher in both healthy and septic neonates compared to adults, and strongly correlated to morbidity and mortality in neonatal sepsis." (PMID 31456998, 2019). "For instance, interleukin (IL)-17A is recognized as a effector of IL-18–mediated injury and the outcomes of neonatal sepsis can be improved by disrupting the IL-18/IL-1/IL-17A axis." (PMID 30497506, 2018). "Targeting the IL-18/IL-17A axis through the use of neutralizing IL-17 receptor antibodies represents a novel approach to treating neonatal sepsis." (PMID 28224121, 2017). "The deleterious effects of IL-18 on neonatal sepsis survival were dependent upon IL-1R1 signaling and IL-17A production by gamma delta cells in the intestine and lung." (PMID 28224121, 2017). "Elevated IL-18 levels have been observed in both adult and neonatal sepsis, especially in non-survivors." (PMID 40510342, 2025).
oral cancer (9 papers, 2013 to 2025). "A significantly different distribution of IL-18 -137 G/C gene polymorphism based on gender, age, alcohol, tobacco, and areca consumption between oral cancer patients and controls was found." (PMID 24349532, 2013). "Adjusted odds ratio (AOR) and 95% confidence intervals (CIs) of oral cancer associated with genotypic frequencies of IL-18 -607A/C and IL-18 -137G/C." (PMID 24349532, 2013). "The participants with G/Cheterozygotes of IL-18 -137polymorphism had a 1.64-fold (95% CI: 1.08-2.48; p=0.02) increased risk of developing oral cancer compared with those with G/G wild type homozygotes." (PMID 24349532, 2013). "The purpose of this study was to identify gene polymorphisms of interleukin-18 (IL-18) -607A/C and -137G/C specific to patients with oral cancer susceptibility and clinicopathological status." (PMID 24349532, 2013). "For -607A/C polymorphism of IL-18, among alcohol consumers, those with A/A homozygotes of IL-18 -607 A/C polymorphism had a 2.38-fold (95% CI=1.17-4.86; p=0.01) increased risk of developing oral cancer compared with those with C/C homozygotes." (PMID 24349532, 2013). "Adjusted odds ratio (AOR) and 95% confidence intervals (CIs) of oral cancer associated with genotypic frequencies of IL-18 -607 A/C and IL-18 -137 G/C among individuals exposure to related environmental risk factors." (PMID 24349532, 2013). "Our study offered information that IL-18 gene promoter polymorphism -137G/C was significantly associated with oral cancer susceptibility and clinicopathological development." (PMID 24349532, 2013). "One of the possible explanations for the controversial effect of IL-18 -137 G/C polymorphism in oral cancer susceptibility and clinical progression is that IL-18 has dual effects on cancer development and progression." (PMID 24349532, 2013). "Unfortunately, their sample size limited the prediction of IL-18 -607A/C and -137G/C gene polymorphisms on the risk of oral cancer." (PMID 24349532, 2013). "Adjusted odds ratio (AOR) and 95% confidence intervals (CI) of clinical statuses associated with genotypic frequencies of IL-18 -607A/C and IL-18-137G/C in oral cancer patients (n=567)." (PMID 24349532, 2013). "People with G/C alleles of IL-18 -137G/C polymorphism had a 1.64-fold (95% CI=1.08-2.48; p=0.02) increased risk of developing oral cancer compared with those with G/G homozygotes." (PMID 24349532, 2013). "However, we also found that G/C genotype IL-18 -137 polymorphism represented a protective factor for oral cancer progression." (PMID 24349532, 2013). "However, among alcohol consumers, people with A/Ahomozygotes of IL-18 -607A/C polymorphism had a 2.38-fold (95% CI=1.17-4.86; p=0.01) increased risk of developing oral cancer compared with those with C/Chomozygotes." (PMID 24349532, 2013). "In conclusion, our results suggest that IL-18 -137 G/C gene polymorphism may be a factor that increases the susceptibility to oral cancer and can be a protective factor against oral cancer progression." (PMID 24349532, 2013). "IL-18 -137G/C gene polymorphism may be a factor that increases the susceptibility to oral cancer, as well as a protective factor for oral cancer progression." (PMID 24349532, 2013). "Also, among alcohol consumers, participants with A/A homozygotes of IL-18 -607 A/C polymorphism had a 2.38-fold (95% CI=1.17-4.86; p=0.01) increased risk of developing oral cancer compared with participants with C/C homozygotes, determined after adjusting for confounders." (PMID 24349532, 2013). "We suggest that IL-18 can act against the occurrence of oral cancer and induce angiogenesis and metastasis, which, in part, play a role in the advanced progression of oral cancer." (PMID 24349532, 2013).
oral cancer (continued). "It has been demonstrated that the expression and secretion of IL-18 is a crucial event against oncogenesis of oral carcinoma cells because of its modulation of cell cycle progression or its triggering of an apoptotic pathway." (PMID 24349532, 2013). "Our study suggests that the over-expression of IL-18 plays a vital role in protecting people from oral cancer." (PMID 24349532, 2013). "We considered that the impact of genetic polymorphisms IL-18 -607A/C and -137G/C differences related to ethnicity, and their interaction with oral cancer related risk factor, including areca, tobacco, and alcohol consumption could increase oral cancer risk among Taiwanese." (PMID 24349532, 2013). "On the contrary, there were also some negative associations reported between IL-18 polymorphisms and the risk of head and neck cancers in Iran, as well as oral cancer in Greece." (PMID 30925760, 2019). "IL-18 has been shown to act as a regulator of oral cancer development." (PMID 24349532, 2013). "Our study suggested that IL-18 polymorphisms -607A/C and -137G/C could regulate the protein levels of IL-18 and considerably affect the individual sensitivity to oral cancer." (PMID 24349532, 2013). "However, the production of IL-18 by PMN was enhanced among oral carcinoma patients after cancer treatment." (PMID 24349532, 2013). "We suggested that IL-18 is a key regulator for the development of oral cancer." (PMID 24349532, 2013). "Furthermore, it is probable that IL-18 acts as both a suppressor and promoter in the regulation of oral cancer development." (PMID 24349532, 2013). "Adjusted odds ratio (AOR) and 95% confidence intervals (CIs) of oral cancer associated with genotypic frequencies of IL-18 -607A/C and IL-18 -137G/C among individuals non-exposure to related environmental risk factors." (PMID 24349532, 2013). "However, there was not a significant association between IL-18 -607A/C genetic polymorphism and oral cancer." (PMID 24349532, 2013). "In an in vitro model employing OSCC cells and an in vivo xenograft model of oral cancer, an NLRP3 inflammasome inhibitor BAY-117082 significantly reduced NLRP3, ASC, caspase-1, IL-1β, and IL-18 expression and a reduction in tumor growth." (PMID 38904007, 2024). "It is found that significantly higher levels of IL-18 in serum and culture supernatants of PMN from patients with oral cancer in Stages III and IV as compared with patients in Stages I and II." (PMID 24349532, 2013). "However, the higher concentrations of IL-18 in serum and culture supernatants of PMN from patients with oral cancer in Stages III and IV as compared with patients in Stages I and II could be the host’s response against the growth and progression of oral cancer." (PMID 24349532, 2013).
psoriatic arthritis (9 papers, 2016 to 2026). Joint inflammation associated with psoriasis. "Ninety pediatric participants (JIA, CD, psoriatic arthritis, healthy controls) underwent serum cytokine profiling (IL-1α, IL-1β, IL-36α, IL-37, IL-6, IL-18, IL-27, IL-31) at baseline and 12 months." (PMID 42196228, 2026). "A higher concentration of IL-18 has also been noted in PsA patients compared to healthy controls, and the authors proposed that IL-18 and IL-20, as well as matrix metalloproteinases 1 and 3, may be suitable markers for the severity of psoriatic arthritis." (PMID 37298045, 2023). "Free IL-18 levels were not increased in neither RA nor in psoriatic arthritis patients as compared to healthy individual." (PMID 36032110, 2022). "It was indicated that free IL-18 serum concentrations are significantly higher in AOSD patients compared to either healthy or disease controls including RA, SLE, axial spondyloarthritis and psoriatic arthritis." (PMID 36032110, 2022). "The pathogenesis of psoriatic arthritis is related to the innate and adaptive immune response involving different proinflammatory cytokine, including TNF, IL-1β, IL-6, IL-22, IL-23, IL-17A, and IL-18." (PMID 36297574, 2022).
silicosis (9 papers, 2006 to 2026). Silicosis is a respiratory disease caused by breathing in (inhaling) silica dust. "Moreover, the characteristic up-regulation in IL-1β and IL-18 inflammatory cytokines associated with silicosis was also substantially mitigated in macrophages under Tet treatment." (PMID 34417574, 2022). "BALF from silicosis mice treated with clodronate liposome showed decreased IL-1β and IL-18 production." (PMID 36459518, 2022). "Increasing evidence highlights the proinflammatory cytokines IL-1β and IL-18 as key drivers in the development of silicosis." (PMID 35130879, 2022). "Intriguingly, in the Atg5fl/flLysM−Cre+ silicosis mice model, the inhibition of autophagy elevates the release of IL-18." (PMID 33466366, 2021). "Activated Caspase-1 triggers the cleavage of proinflammatory cytokines, interleukin 1-beta and interleukin 18 for subsequent activation and secretion, which is likely to be part of the pathway leading to silicosis." (PMID 21311600, 2011). "Notably, RAB20 deficiency was associated with significantly higher concentrations of IL-1β and slightly higher concentrations of IL-18 in the BALF when compared to WT mice established with silicosis." (PMID 36131930, 2022). "In the future, the obstruction of the release of IL-18 mediated by autophagy may be involved in the silicosis treatment." (PMID 33466366, 2021). "Since proinflammatory cytokines drive the progression of silicosis, we performed ELISA to measure the cytokine levels in the BALF and found the increased release of IL-1β and IL-18 in mice receiving intratracheal silica crystal suspension." (PMID 36131930, 2022). "Pathways other than IL-12 and IL-18 appear to be driving lymphocyte activation and recruitment and IFN-γ production in silicosis, with IL-15 a likely candidate." (PMID 16396683, 2006).
uveitis (9 papers, 2019 to 2023). An inflammatory process affecting a part of or the entire uvea. "In this report, we investigated the status of NK cells and their role in uveitis, and tested the capacity for IL‐18 to influence NK cell status in uveitis." (PMID 30548211, 2019). "In our study, we now provide evidence indicating that IL‐18 is a pathogenic factor in EAU and provide a description for some possible mechanisms of IL‐18 in uveitis." (PMID 30548211, 2019). "In addition, targeting IL-1 or IL-18 signaling is an effective and possible strategy to control ocular inflammation in autoinflammatory diseases, such as uveitis." (PMID 35836195, 2022). "And then, the possible cell subsets involved in secreting IL‐18 in uveitis were measured." (PMID 30548211, 2019). "When comparing uveitis entities, the B27+ AAU group showed significantly increased levels of IL-2, IL-6, IL-18, IL-22, IL-1β, and interferon (IFN)-γ." (PMID 34783307, 2021). "The analysis of the cytokine pattern of AqH and sera in the study confirmed previous observations describing elevated IL-18 and IFN-γ levels in the AqH, and an elevated serum IFN-γ level in B27+ AAU patients during active uveitis." (PMID 34783307, 2021). "The increases in IL‐18 observed in EAU might represent an important factor which promotes CD83+CCR7+ NK cell activation, thereby participating in the development of uveitis." (PMID 30548211, 2019).
allergic asthma (8 papers, 2012 to 2024). A asthma with a basis in a pathological type I hypersensitivity reaction. "IL-18 levels were higher in allergic asthma group compared with the others.IL-18 protein was strongly expressed in airway epithelium cells and smooth muscle cells, while IL-18Rα was expressed only on airway epithelium." (PMID 39554494, 2024). "On the other hand, when IL-12 was co-administered with IL-18 in a murine allergic asthma model, the appearance of Th2 cytokines was abolished." (PMID 33803752, 2021). "In severe allergic asthma patients, who typically respond to omalizumab (anti-IgE therapy), high baseline serum free IL-18 levels may predict reduced omalizumab efficacy." (PMID 39554494, 2024). "However, in a ragweed murine model of allergic asthma, administration of IL-18 together with the allergen increased the production of IL-5 by splenocytes cultured in the presence of ragweed." (PMID 33803752, 2021). "In the present study, IL-18 levels were dramatically high in M/S PAR group, reflecting that this cytokinemight be involved in the pathogenesis of allergic asthma." (PMID 36032502, 2022). "RSV-induced bronchiolitis is correlated with the occurrence of atopic and allergy asthma, and IL12 and IL18 play critical roles in Th1 and/or Th2 immune responses to airway inflammation induced by RSV infection." (PMID 31223533, 2019). "Finally, rBCG::IL-18 and rBCG::PTA have been demonstrated to reduce Th2 cytokine production and eosophil influx in the lungs, as well as to improve lung function in ovalbumin mouse models of allergic asthma." (PMID 35632582, 2022).
breast tumor (8 papers, 2011 to 2024). "Similar to our study, lysates from chemosensitive breast tumors had lower IL18 protein levels compared to chemoresistant tumors." (PMID 37533202, 2023). "Following CCL2 expression, the present result demonstrated that IL18 expression is downregulated in breast tumor tissue exposed to ECCT treatment." (PMID 32695310, 2019). "This study aims to elaborate on the association of CCL2, IL18, IL23α, and TNF-α (tumor necrosis factor-alpha) expression with the anti-proliferative effect of ECCT in rat breast tumor tissue." (PMID 32695310, 2019). "To determine if exposure to these 3 cytokines simultaneously would affect the ability of NK cells to kill breast tumor cells, we isolated NK cells from human PBMCs and stimulated them in an IL-15/IL-12/IL-18 rich environment for 16 hours." (PMID 25879689, 2015). "Among them, the elevated expression of IL-18 in doxorubicin-resistant cell lines and breast tumor tissues was validated and its role in doxorubicin resistance was further confirmed by cell viability experiments in the presence or absence of this protein." (PMID 21931812, 2011). "Therefore, our result suggested that decreasing CCL2 and IL18 expression in the breast tumor microenvironment is most probably due to AC-EF treatment." (PMID 32695310, 2019). "In contrast, IL18, IL2RG, IL33 and MAPK10 were highly expressed in normal breast tissues, whereas they were expressed at low levels in breast tumor tissues (p < 0.001)." (PMID 38438469, 2024). "In rat breast tumor tissues of IT groups, the mRNA expression of CCL2 and IL18 are significantly down-regulated, in contrast with the up-regulated expression of these cytokines in tumor tissues of the INT group." (PMID 32695310, 2019). "IFNγ production by peripheral NK cells from HCC patients in response to IL-12 and IL-18 was in keeping with that of another HCC cohort and by tumor-infiltrating NKs was similar to that seen in NK cells infiltrating breast tumors." (PMID 29867983, 2018). "Other up-regulated proteins of interest with possible roles in regulating breast tumor cell progression included DPYSL2, FAM129B, IL18, NDRG1, NME1, and SERPINB5." (PMID 28174229, 2017).